UGCG (UDP-glucose ceramide glucosyltransferase)
Description:
Participates in the initial step of the glucosylceramide-based glycosphingolipid/GSL synthetic pathway at the cytosolic surface of the Golgi. Catalyzes the transfer of glucose from UDP-glucose to ceramide to produce glucosylceramide/GlcCer (such as beta-D-glucosyl-(1<->1')-N-acylsphing-4-enine). GlcCer is the core component of glycosphingolipids/GSLs, amphipathic molecules consisting of a ceramide lipid moiety embedded in the outer leaflet of the membrane, linked to one of hundreds of different externally oriented oligosaccharide structures. Glycosphingolipids are essential components of membrane microdomains that mediate membrane trafficking and signal transduction, implicated in many fundamental cellular processes, including growth, differentiation, migration, morphogenesis, cell-to-cell and cell-to-matrix interactions (By similarity). They are required for instance in the proper development and functioning of the nervous system (By similarity). As an example of their role in signal transduction, they regulate the leptin receptor/LEPR in the leptin-mediated signaling pathway (By similarity). They also play an important role in the establishment of the skin barrier regulating keratinocyte differentiation and the proper assembly of the cornified envelope (By similarity). The biosynthesis of GSLs is also required for the proper intestinal endocytic uptake of nutritional lipids (By similarity). Catalyzes the synthesis of xylosylceramide/XylCer (such as beta-D-xylosyl-(1<->1')-N-acylsphing-4-enine) using UDP-Xyl as xylose donor.
Synonyms: GCS; GLCT1
Tractability: Small molecule: an approved drug acts on it; a high-quality ligand is known; it belongs to a druggable protein family. Antibody: UniProt predicts a signal peptide or a membrane-spanning region. PROTAC: ubiquitination databases record sites on it; its protein half-life has been measured; a small molecule that binds it is known.
Target class: Enzyme; Transferase
Chemical probes: T-036 (high quality), T-690 (high quality)
Gene: Protein-coding gene on chromosome 9 (111,896,814 to 111,935,374, forward strand). Ensembl gene ENSG00000148154.
Subcellular location: Golgi apparatus membrane
Pathways (Reactome):
Metabolism: Glycosphingolipid biosynthesis
Gene Ontology:
Molecular function: ceramide glucosyltransferase activity; protein binding; glycosyltransferase activity
Biological process: glucosylceramide biosynthetic process; cell differentiation; cornified envelope assembly; epidermis development; establishment of skin barrier; glycosphingolipid biosynthetic process; intestinal lipid absorption; keratinocyte differentiation; leptin-mediated signaling pathway; neuron development; protein lipidation; regulation of signal transduction; sphingolipid metabolic process
Cellular component: Golgi membrane; membrane
Genetic constraint (gnomAD): Loss-of-function variants: 7 observed, 36.53 expected, observed/expected ratio (o/e) 0.19, 90% interval 0.11 to 0.36. The upper end of that interval is the gene's LOEUF score, 0.36, which puts it in group 1 of 6, group 1 being the genes least tolerant of losing a copy. Missense variants: 244 observed, 401.43 expected, observed/expected ratio (o/e) 0.61, 90% interval 0.55 to 0.68. Synonymous variants: 158 observed, 136.62 expected, observed/expected ratio (o/e) 1.16, 90% interval 1.01 to 1.32.
Homologues: Orthologues: chimpanzee UGCG (100% identical), macaque UGCG (100% identical), dog UGCG (99% identical), pig UGCG (99% identical), mouse Ugcg (98% identical), guinea pig UGCG (97% identical), rat Ugcg (97% identical), tropical clawed frog ugcg (92% identical), rabbit UGCG (92% identical), zebrafish ugcg (91% identical), Drosophila melanogaster GlcT (52% identical), Caenorhabditis elegans cgt-3 (44% identical), and 2 more.
Diseases named in the same sentence as UGCG in open-access papers:
UGCG is named in the same sentence as 106 diseases in open-access papers, as found by Europe PMC text mining. Sharing a sentence is not in itself a finding about the gene and the disease. The quoted sentences say what the papers report.
breast cancer (20 papers, 2015 to 2025). A primary or metastatic malignant neoplasm involving the breast. "To find the association between ZFX and UGCG in luminal breast cancer patients, we analyzed the TCGA-BRCA and METABRIC patient gene expression datasets." (PMID 40934285, 2025). "To further validate the association of ZFX and UGCG in breast cancer patients, we quantified the expression of UGCG and ZFX by immunohistochemical (IHC) analysis in tumor samples of all subtypes (N = 90)." (PMID 40934285, 2025). "Additionally, UDP-glucose ceramide glucosyl transferase (UGCG) overexpression in breast cancer cells is associated with increased glutamine uptake and utilization, linking glycosphingolipid metabolism to glutamine metabolism." (PMID 39408832, 2024). "In line with our findings in human cell culture and mouse models, we observe an elevated expression of RICTOR, ZFX, and UGCG in Indian luminal breast cancer tissues and in TCGA and METABRIC datasets." (PMID 40934285, 2025). "To decipher the effect of increased glucosylceramides on tumor progression, we overexpressed UGCG transcript-encoding cDNA in MCF-7 (MCF-7_UGCGOE) and BT-474 (BT-474_UGCGOE) cells representing the luminal breast cancer subtype." (PMID 40934285, 2025). "In parallel, overexpression of UGCG enhances oxidative phosphorylation and glycolysis in breast cancer cells, whereas UGCG knockdown in cervical cancer cells impairs glucose uptake, lactate production, and ATP synthesis." (PMID 41155172, 2025). "In breast cancer cells, the overexpression of UGCG was shown to increase glycolysis and oxidative phosphorylation." (PMID 35631574, 2022). "UGCG overexpression increases both glycolysis, oxidative phosphorylation, and amino acid synthesis in breast cancer cells." (PMID 36232480, 2022). "In a novel study, the overexpression of UDP-glucose ceramide glucosyltransferase (UGCG) in breast cancer cells resulted in higher levels of both glucosylceramide and lactosylceramide in the ER and mitochondria." (PMID 33673027, 2021). "UDP-glucose ceramide glucosyltransferase (UGCG), a key enzyme in glycosphingolipid metabolism, is overexpressed in metastatic breast cancer cells and augmented glutamine uptake for cellular energy metabolism." (PMID 33854965, 2021). "Previous studies revealed that UDP-glucose ceramide glucosyltransferase (UGCG) overexpression (OE) leads to alterations of GEM composition in breast cancer cells resulting in signaling pathway activation and subsequently altered gene expression." (PMID 32424263, 2020). "In previous studies, we were able to show that glutamine is used for reinforced oxidative stress response via glutathione production and fuels the TCA cycle to sustain the proliferative advantage of UGCG overexpressing breast cancer cells." (PMID 32424263, 2020). "With this study we were able to show that UGCG overexpression (OE) mediates a metabolic transformation from a quiescent/aerobic to energetic breast cancer cell type indicated by increased glycolysis and OXPHOS." (PMID 32424263, 2020). "Previously, we showed an UGCG-dependent glutamine metabolism adaption to nutrient-poor environment of breast cancer cells." (PMID 32424263, 2020). "Our results show that UGCG overexpression leads to increased ROS defense mechanisms in breast cancer cells." (PMID 31666638, 2019). "We investigated the influence of UGCG overexpression on glutamine metabolism in breast cancer cells." (PMID 31666638, 2019). "The proliferation assay results show that glutamine is essential for the proliferation advantage of MCF-7/UGCG OE cells indicating a glutamine dependency of breast cancer cells following UGCG overexpression." (PMID 31666638, 2019). "Beside its essential functions especially in the maintenance of the epidermal water barrier function, UGCG is overexpressed in several cancer types for example in metastatic breast cancer tissue leading to poor patient prognosis." (PMID 29409484, 2018).
breast cancer (continued). "UGCG blockage resensitizes multidrug resistant breast cancer cell to anticancer drugs via downregulation of MDR1." (PMID 29409484, 2018). "It has been found that increased expression of UGCG is correlated to the progression of breast cancer, renal cancer, ovarian cancer and leukemia and is frequently correlated with MDR1 levels in tumor samples." (PMID 26474061, 2015). "Metastatic breast cancer-overexpressing UGCG indicated that glutamine could be a precursor of other amino acid syntheses, such as aspartate and proline." (PMID 33854965, 2021). "Our data indicate that UGCG is closely connected to the breast cancer cell energy metabolism." (PMID 32424263, 2020). "UGCG OE mediates increased glycolysis in breast cancer cells." (PMID 32424263, 2020). "Additionally, overexpression of UGCG in MCF-7 breast cancer cells enhanced proliferation and promoted doxorubicin resistance." (PMID 32577155, 2020). "With this study we were able to show that UGCG overexpression in breast cancer cells leads to increased mRNA expression of glutamine metabolizing enzymes resulting in an increased oxidative stress response and increased glutamine oxidation to provide sufficient energy for cell proliferation." (PMID 31666638, 2019). "Potential side effects of GPNA, CB-839 or others could be reduced by lowering the dose and drug efficacy could be increased by co-treatment with UGCG inhibitors, because we assume that both inhibitors would work synergistically in the process of inhibiting breast cancer cell proliferation." (PMID 32424263, 2020). "Interestingly, in previous studies we could show that UGCG overexpression leads to activation of the Akt signaling pathway in breast cancer cells." (PMID 31666638, 2019). "To assess the correlation of RICTOR, UGCG, and ZFX in cancer cells, we analyzed publicly available single-cell RNA sequencing datasets from breast cancer patients (GSE176078)." (PMID 40934285, 2025). "Although our study is focused on luminal breast cancer, we have shown that ZFX also regulates UGCG expression in other cancer cell lines." (PMID 40934285, 2025). "In cervical and breast cancer, overexpression of UDP-glucose ceramide glucosyltransferase (UGCG) led to increased synthesis of glucosylceramide and subsequently more complex GSLs to fuel cell proliferation and glycolysis via the PI3K/AKT pathway." (PMID 39628991, 2024). "In the current study we show that UGCG OE increases substrate oxidation and OXPHOS in breast cancer cells." (PMID 32424263, 2020). "Interestingly, in UGCG overexpressing breast cancer cells, no changes in dhCer concentrations in ER/mitochondria fractions were detected." (PMID 34626204, 2021).
Gaucher disease (18 papers, 2010 to 2025). Gaucher disease (GD) is a lysosomal storage disorder encompassing three main forms (types 1, 2 and 3), a fetal form and a variant with cardiac involvement (Gaucher disease - ophthalmoplegia - cardiovascular calcification or Gaucher-like disease). "Tumors with deregulated gangliosides synthesis can be responsive to treatment with UGCG inhibitors, such miglustat and eliglustat, which are already used in the clinic for the treatment of children with Gaucher disease." (PMID 39449099, 2024). "Interestingly, Miglustat and Ibiglustat, two inhibitors of UGCG UDP-glucose ceramide glucosyltransferase that are being used to reduce GlcCer levels in Gaucher disease patients, did not reduce the bang-sensitivity in INAD flies." (PMID 36645408, 2023). "Interestingly, emerging oncology and non-oncology drugs such as the HDAC inhibitors and miglustat, an approved drug for Gaucher’s disease, were amongst potential drug repurposing candidates that target fitness genes in tractability group 1 (targeting HDAC2 and UGCG respectively)." (PMID 32990596, 2020).
colon carcinoma (9 papers, 2012 to 2025). "Inhibition of UGCG inhibits colon cancer cell growth in vitro and induced colon cancer development in mice." (PMID 41155172, 2025). "Consistent with the pro-apoptotic role of ceramide, the increased expression of UGCG in colon cancer cells was found to promote multidrug resistance through the depletion of ceramide levels." (PMID 30011843, 2018). "To confirm if RICTOR-mediated UGCG regulation exists in other cell types, we silenced RICTOR in HCT-116 (human colon cancer cells) and HEK-293 (human embryonic kidney) cells and observed a decrease in glucosylceramides." (PMID 40934285, 2025). "Inhibition of UGCG inhibits colon cancer cell growth in vitro and AOM/DSS-induced colon cancer development in mice and increases SM which is stored in multi-vesicular bodies." (PMID 38635059, 2024).
melanoma (8 papers, 2015 to 2025). A malignant, usually aggressive tumor composed of atypical, neoplastic melanocytes. "Accordingly, various human melanoma cells displayed a SL metabolism signature associated with (i) a robust and a low expression of UGCG and SGMS1/2, respectively, (ii) higher in situ enzyme activity of GCS than SMS, and (iii) higher intracellular levels of GlcCer than SM." (PMID 31114500, 2019). "Furthermore, GM95, an UGCG deficient cell line derived from the mouse melanoma B16 cells, was also resistant to elisidepsin." (PMID 26474061, 2015). "We selected the best candidate from a battery of shRNAs for each of these genes and confirmed through viability assay that individually knocking down ST3GAL5, B4GALT5 or UGCG diminished the cytotoxicity of both AgGom and HiGom in melanoma cells." (PMID 41271646, 2025). "The combination of NNC with D-threo-PPMP (PPMP), a UDP-glucose ceramide glucosyltransferase(UGCG) inhibitor, further improved the antitumor activity of MAPKi in melanoma models." (PMID 40617808, 2025). "Accordingly, melanoma cells exhibited low SGMS1 and SGMS2 expression, while they expressed UGCG at higher levels." (PMID 31114500, 2019). "For this purpose we used the mouse melanoma B16 cell line and its mutant derivative GM95, described to lack UDP-glucose:ceramide glucosyltransferase (UGCG; EC 2.4.1.80) activity." (PMID 26474061, 2015). "Therefore, we followed up by using shRNA knock-down in melanoma cells to target the hits identified from our CRISPR KO screen (ST3GAL5, B4GALT5, UGCG, p < 0.05, FDR < 0.2)." (PMID 41271646, 2025). "Moreover, melanoma expressed SGMS2 at rather low levels, while expressing UGCG at high levels." (PMID 31114500, 2019). "Furthermore, GM95, a mutant derivative from B16 mouse melanoma cells lacking ceramide glucosyltransferase (UGCG) activity and thus the synthesis of glycosylceramides, was also resistant to elisidepsin." (PMID 26474061, 2015).
lysosomal storage disorder (6 papers, 2012 to 2025). "In addition, AFD, an inherited lysosomal storage disorder that frequently results in renal failure, hypertensive cardiac disease, and vascular disease, is linked to UGCG." (PMID 37274734, 2023). "Enhancing the effectiveness of both cell‐ and antibody‐based therapies against nsGSL‐expressing tumors could be achieved by specific inhibitors of GSL synthesis such as Eliglustat or Miglustat (UGCG inhibitors) which are currently safely applied to patients with lysosomal storage disorders." (PMID 39655358, 2025).
Fabry disease (5 papers, 2017 to 2025). Fabry disease (FD) is a progressive, inherited, multisystemic lysosomal storage disease characterized by specific neurological, cutaneous, renal, cardiovascular, cochleo-vestibular and cerebrovascular manifestations. "In humans, diabetes is associated with changes in the kidney expression of genes encoding enzymes in the Gb3 pathway, including upregulation of UGCG, a therapeutic target in Fabry disease." (PMID 37958836, 2023). "Especially in the condition where Fabry disease and diabetes coexist, the high expression of UGCG may lead to more severe kidney phenotypes." (PMID 41049486, 2025).
viral infection (5 papers, 2021 to 2025). "Pharmacologic inhibition of UGCG using ibiglustat resulted in NK cell apoptosis, loss of cytotoxic granules, impaired expansion during viral infection, and disrupted granule integrity." (PMID 40903462, 2025). "GlcCer supplement in SPT-KO or UGCG-KO cells robustly facilitated viral infection to the similar levels of viral infection in control or UGT8-KO cells." (PMID 36920967, 2023). "The inhibition of UGCG synthesis may be a beneficial approach for the treatment of viral infection of the CNS." (PMID 37168733, 2023). "Genetic deletion or pharmacologic inhibition of UGCG disrupted cytotoxic granules, induced apoptosis, and blocked NK and CD8+ T cell expansion during viral infection, underscoring the critical role of glycosphingolipid metabolism in lymphocyte identity and effector function." (PMID 40903462, 2025). "The UGCG gene (ceramide to glucosylceramide) and its immediate downstream gene B4Galt5 (glucosylceramide to lactosyl ceramide) have recently been shown to be ‘super-enhancers’ changing the cell phenotype, being essential for NK cells and CD8+ cytotoxic cells in their response to viral infection." (PMID 41227379, 2025).
glioma (4 papers, 2015 to 2025). A benign or malignant brain and spinal cord tumor that arises from glial cells (astrocytes, oligodendrocytes, ependymal cells). "The IHC findings confirmed the increased expression of AEBP1, DCTD, DEPP1, DUSP6, FKBP9, and UGCG with the up‐regulation of glioma grades." (PMID 40052358, 2025). "Transwell migration and invasion assays were performed to evaluate cellular behavior, and the results showed a significantly decreased ability of migration and invasion of glioma cell lines after the knocking down of UGCG." (PMID 40052358, 2025). "In this study, we performed in vitro experiments to investigate the role of UGCG within glioma cell lines." (PMID 40052358, 2025). "Our findings revealed that UGCG could enhance glioma cell proliferation, migration, and invasion while reducing apoptotic capacities." (PMID 40052358, 2025). "In vitro experiments showed that UGCG could promote glioma cell proliferation, migration, and invasion, while decreasing apoptosis." (PMID 40052358, 2025). "We further explored the role of UGCG with two glioma cell lines." (PMID 40052358, 2025). "Among them, PCOLCE2, ERP27, PSMD13, C14orf39, C16orf86, UGCG, and HPX were identified as prognostic factors for glioma for the first time." (PMID 35873494, 2022).
breast tumor (3 papers, 2020 to 2025). "It is also noteworthy that from the bar chart view, selecting UGCG or SREBF1 as potential biomarkers would be unlikely as most normal breast tumour samples also expressed high levels of these genes." (PMID 32577155, 2020). "Amongst other genes upregulated in breast tumour tissue was UGCG (1.13-fold change), regulated by both hsa-miR-128 and hsa-miR-223, which is involved in drug resistance." (PMID 32577155, 2020).
colorectal cancer (3 papers, 2020 to 2024). A primary or metastatic malignant neoplasm that affects the colon or rectum. "Moreover, elevated UGCG gene expression correlated with decreased disease-free survival in colorectal cancer patients and could provide a novel prognostic marker in colorectal cancer." (PMID 39337312, 2024).